APLN (apelin)
Diseases named in the same sentence as APLN in open-access papers (continued):
Sharing a sentence is not in itself a finding about the gene and the disease.
hereditary pulmonary arterial hypertension (2 papers, 2021 to 2024). "Mutations in the bone morphogenetic protein receptor type II (BMPR-II) result in reduced plasma levels of apelin in patients with heritable pulmonary arterial hypertension." (PMID 33171278, 2021). "Indeed, we observed dysregulation of KRIT1, related to cerebral cavernous malformations (CCM), APLN, related to lymphatic malformations, GNA11 related to capillary malformations and BMPR2, related to arteriovenous malformations and hereditary pulmonary arterial hypertension (HHT)." (PMID 38771392, 2024).
homeostasis (2 papers, 2012 to 2019). "This association is dependent on impaired glucose homeostasis, and disappears after bariatric surgery, providing further evidence regarding the relationship between apelin and the regulation of glucose metabolism." (PMID 23227256, 2012). "Apelin participates in cardiovascular functions, metabolic disease, and homeostasis disorder." (PMID 31270645, 2019).
hyperandrogenism (2 papers, 2022 to 2025). Excessive secretion of androgens from the adrenal glands or gonads. "Concentrations of ADPN, apelin, leptin, omentin, resistin, visfatin, and the L/A ratio were found to correlate with parameters of lipid metabolism in girls diagnosed with menstrual disorders and hyperandrogenism." (PMID 41303021, 2025). "As regards apelin, the relationship between this adipocytokine and PCOS hyperandrogenism has been widely studied and appears mostly indirect." (PMID 35701786, 2022).
inflammatory bowel disease (2 papers, 2023 to 2024). A spectrum of small and large bowel inflammatory diseases of unknown etiology. "High apelin levels have been shown to exacerbate inflammation and contribute to disease flare-ups in conditions such as inflammatory bowel disease (IBD)." (PMID 39335642, 2024).
ischemic disease (2 papers, 2016). Lack of blood supply to an area of the body, resulting in impairment of tissue oxygenation. "Thus, combinatorial injection of hypoxic PBMNCs and apelin-13 could be an effective therapeutic strategy for patients with severe ischemic diseases." (PMID 26763337, 2016). "Our BLI observation has consolidated that apelin may enhance the functional survival of AD-MSCs in experimental PAD, thus providing a promising measure for future stem cell-based therapy in ischemic diseases." (PMID 26902855, 2016).
limb ischemia (2 papers, 2016 to 2023). A ischemia that involves the limb. "Following limb ischemia, blood flow reperfusion, functional recovery of the limb and vascular density were improved in diabetic mice receiving Pyr-apelin-13 compared to untreated diabetic mice." (PMID 37636297, 2023). "In this study, we examined whether apelin-13, a regulator of vessel maturation, could be an effective promoter of therapeutic angiogenesis, following severe limb ischemia." (PMID 26763337, 2016). "We observed a 42% reduction (P = 0.0026) in apelin plasma levels in diabetic mice in response to limb ischemia compared to nondiabetic mice." (PMID 37636297, 2023).
lipid metabolic disorders (2 papers, 2021 to 2023). "Human studies have shown that the serum levels of Apelin-13, Apelin-36, and NO are higher in patients with GDM than in healthy mothers in the second trimester of pregnancy, who suffer from glucose and lipid metabolism disorders." (PMID 38089606, 2023). "Second, we found that SARS-CoV-2 infection could modulate the expression of MPO, apelin, and myostatin by up-regulating transcription factor REST, which may lead to glucose and lipid metabolic disorders." (PMID 34916489, 2021).
metastatic colorectal cancer (2 papers, 2021 to 2025). "We explore the therapeutic potential of targeting proapelin cleavage sites in metastatic colorectal cancer by introducing apelin-dm, a modified variant resulting from alteration in proapelin cleavage sites." (PMID 39962271, 2025).
metastatic prostate carcinoma (2 papers, 2022 to 2025). A carcinoma that arises from the prostate gland and has spread to other anatomic sites. "We propose that the apelin/integrin axis represents a novel therapeutic target for treating metastatic prostate cancer." (PMID 40612675, 2025). "Our results suggest that the apelin/integrin axis is a novel therapeutic target for treating metastatic prostate cancer." (PMID 40612675, 2025). "Targeting the apelin/integrin αvβ3 axis may serve as a potential therapeutic strategy for treating metastatic prostate cancer." (PMID 40612675, 2025). "Increasing miR-106a-5p synthesis via the c-Src/PI3K/Akt pathway regulated the effects of apelin, indicating that apelin may be worth targeting in metastatic prostate cancer." (PMID 36291151, 2022). "The evidence indicates that apelin is a promising therapeutic object in metastatic prostate cancer." (PMID 36291151, 2022). "Thus, apelin is a promising therapeutic target for curing metastatic prostate cancer." (PMID 36291151, 2022). "Interestingly, apelin expression was higher in metastatic prostate cancer (androgen receptor [AR] positive) compared to nonmetastatic disease." (PMID 36291151, 2022).
Moyamoya disease (2 papers, 2022). Moyamoya disease (MMD) is a rare intracranial arteriopathy involving progressive stenosis of the cerebral vasculature located at the base of the brain causing transient ischemic attacks or strokes. "A clinical trial demonstrated that apelin-13 was significantly increased in patients with moyamoya disease compared to those with middle cerebral artery occlusion independent of NO and VEGF." (PMID 36034795, 2022).
myopia (2 papers, 2023 to 2025). "Our previous study revealed that the lncRNA-XR_002792574.1/miR-760-3p/Adcy1 axis inhibited the cGMP/PKG and apelin signaling pathways in RGCs, resulting in myopia-related RGC damage." (PMID 39894836, 2025). "However, it is still unknown whether apelin is associated with RGC damage in myopia." (PMID 37932794, 2023). "Furthermore, we explored the cGMP/PKG and apelin pathways in the retinas of adults with high myopia." (PMID 37932794, 2023). "On the one hand, the lncRNA-XR_002792574.1/miR-760-3p/Adcy1 axis might inhibit the cGMP/PKG and apelin signaling pathways in RGCs, thereby causing RGC damage in myopia." (PMID 37932794, 2023). "In future myopia studies, we plan to further verify whether inhibiting lncRNA-XR_002792574.1 regulates the cGMP/PKG and apelin signaling pathways in RGCs and scleral remodeling via miR-760-3p/Adcy1, thereby delaying myopia progression." (PMID 37932794, 2023). "In conclusion, these findings indicate that miR-760-3p/Adcy1 may be involved in the development of myopia in highly myopic adults, that the cGMP/PKG pathway in highly myopic adults is inhibited, and that the apelin pathway shows a downward expression trend in highly myopic adults." (PMID 37932794, 2023).
osteosarcoma (2 papers, 2023 to 2025). A usually aggressive malignant bone-forming mesenchymal neoplasm, predominantly affecting adolescents and young adults. "The levels of APLN expression were significantly associated with osteosarcoma clinical stages." (PMID 36632453, 2023). "Our investigations also revealed that the levels of APLN and PLOD2 expression are positively associated with tumor staging in patients with osteosarcoma." (PMID 36632453, 2023). "An analysis of records from the Gene Expression Omnibus (GEO) database showed higher levels of APLN expression in osteosarcoma tissue than in normal tissue." (PMID 36632453, 2023). "In this study, we found that APLN enhances human osteosarcoma cell migration and the development of lung metastasis was inhibited in mice injected with APLN knockdown cells." (PMID 36632453, 2023). "The results indicate that circ_0000004 acts as a sponge of miR-1303 and thus facilitates APLN-induced osteosarcoma cell migration and increases PLOD2 expression." (PMID 36632453, 2023). "Similarly, the analysis of osteosarcoma tissue samples from the GEO dataset (GSE12685) showed that levels of APLN mRNA expression were higher in osteosarcoma tissue than in primary osteoblasts." (PMID 36632453, 2023). "We also found that knockdown of APLN antagonized lung metastasis in mice with osteosarcoma." (PMID 36632453, 2023). "This study therefore investigated whether APLN affects osteosarcoma migration and examined the involvement of signaling pathways." (PMID 36632453, 2023). "We could therefore only use the OS804D array, which contains two stage IVB osteosarcoma tissue samples (showing significantly high levels of APLN expression)." (PMID 36632453, 2023). "APLN appears to be an appropriate therapeutic target for osteosarcoma." (PMID 36632453, 2023). "In addition, levels of APLN expression in osteosarcoma tissue were higher than in normal bone tissue." (PMID 36632453, 2023). "APLN may be a therapeutic target in osteosarcoma metastasis." (PMID 36632453, 2023). "In conclusion, our study demonstrates that APLN promotes PLOD2 expression and the migration of human osteosarcoma cells via the MST1, MOB1 and YAP signaling cascades and hsa_circ_0000004/ miR-1303 axis." (PMID 36632453, 2023). "Our results found that APLN increases the expression of PLOD2 in osteosarcoma tissue, and thereby promotes osteosarcoma cell migration and induces osteosarcoma metastasis." (PMID 36632453, 2023). "In our study, we found that stimulating cells with APLN prevented YAP phosphorylation, YAP-14-3-3 binding and osteosarcoma cell migration." (PMID 36632453, 2023). "The adipokine apelin (APLN) is also found in different cancers and APLN upregulation promotes angiogenesis and metastasis, but its effects on osteosarcoma metastasis are uncertain." (PMID 36632453, 2023). "We found that inhibition of YAP expression significantly reduced levels of PLOD2 expression and osteosarcoma cell migration, while transfecting osteosarcoma cells with MST1 and MOB1 siRNAs significantly reduced APLN-induced promotion of YAP binding to the PLOD2 promoter region." (PMID 36632453, 2023). "Levels of APLN and PLOD2 protein correlated positively with osteosarcoma clinical stages." (PMID 36632453, 2023). "A positive correlation was found between APLN and PLOD2 expression in osteosarcoma tissue." (PMID 36632453, 2023). "Similarly, our study shows that minoxidil suppresses APLN-induced promotion of PLOD2 expression, leading to the inhibition of osteosarcoma cell migration." (PMID 36632453, 2023). "We examined whether these five signaling pathways mediate APLN-induced increases in PLOD2 expression and promote osteosarcoma cell migration." (PMID 36632453, 2023). "Similarly, levels of APLN and PLOD2 mRNA synthesis were upregulated in osteosarcoma tissue." (PMID 36632453, 2023).
pancreatic adenocarcinoma (2 papers, 2022). "Herein, we report the expression of apelin and its receptor, APJ, in human pancreatic adenocarcinoma and its protumoral function." (PMID 36142542, 2022).
periodontal disease (2 papers, 2023). "Sub-gingival plaque and saliva-serum cytokine levels were measured in patients with OSA in a study; OSA was found to be associated with worsening periodontal disease and greater amounts of IL-6 and apelin in the saliva, as well as changed the bacteria that were examined in plaque." (PMID 37803323, 2023).
psoriasis (2 papers, 2020 to 2023). An autoimmune condition characterized by red, well-delineated plaques with silvery scales that are usually on the extensor surfaces and scalp. "In addition, tryptanthrin displayed anti-angiogenic effect by improving skin lesions in psoriasis through regulation of ERK1/2 MAPK and PI3K-mediated expression of apelin." (PMID 32120929, 2020).
psychosis (2 papers, 2020). "However, other studies have shown controversial roles of APLN in psychosis." (PMID 32849850, 2020).
pulmonary embolism (2 papers, 2022 to 2024). The obstruction of the pulmonary artery or one of its branches by an embolus, sometimes associated with infarction of the lung. "In conclusion, this study adds to the growing body of research examining the serum concentration of Apelin-13 and its potential as a biomarker in individuals with suspected pulmonary embolism (PE)." (PMID 38565984, 2024). "Apelin, fibulins, haemopexin, a2-macroglobulin, Ig a1-chain C region, TNF-α, HMGB1, neutrophil-to-lymphocyte ratio and albumin are among the other biomarkers whose effectiveness has been investigated in the diagnosis of pulmonary embolism." (PMID 36115957, 2022).
Skeletal muscle atrophy (2 papers, 2023 to 2024). The presence of skeletal muscular atrophy (which is also known as amyotrophy). "Thus, this study aimed to investigate the association between apelin and skeletal muscle atrophy in CKD and evaluate the potential of apelin as a therapeutic agent for skeletal muscle atrophy in CKD." (PMID 36562292, 2023). "Administration of apelin ameliorates skeletal muscle atrophy in CKD mice; therefore, targeting the apelin–Apj system could be a promising therapeutic strategy for the management of skeletal muscle atrophy in CKD." (PMID 36562292, 2023). "In addition, treatment with apelin also decreased the expression of muscle RING‐finger protein 1 (MuRF‐1), a skeletal muscle atrophy‐related ubiquitin E3 ligase, compared with treatment with IS alone." (PMID 36562292, 2023).
uremia (2 papers, 2014 to 2020). A clinical syndrome associated with the retention of renal waste products or uremic toxins in the blood. "In another study, apelin has been reported to decrease osteoblastic differentiation of vascular smooth muscle cells and vascular calcification which are important in the pathogenesis of CVD in uremia." (PMID 24433492, 2014).
Anorexia (1 paper, 2024). Lack of desire to eat (loss of appetite). "In sturgeon, CART and Apelin have bidirectional effects including anorexia action in the short term." (PMID 38672450, 2024).
astrocytoma (1 paper, 2022). "However, the elevated APLN expression did not display inferior OS in LGG patients without seizure history (p = 0.1032), with recurrent tumor (p = 0.6446), with astrocytoma (p = 0.115) or oligoastrocytoma (p = 0.108)." (PMID 36193059, 2022). "The high APLN expression was not correlated with RFS in LGG patients without seizure history (p = 0.7572), with recurrent tumor (p = 0.1468), without targeted molecular therapy (p = 0.462), with astrocytoma (p = 0.7805), or with oligoastrocytoma (p = 0.0809)." (PMID 36193059, 2022).
autoimmune disease (1 paper, 2020). A disorder resulting from loss of function or tissue destruction of an organ or multiple organs, arising from humoral or cellular immune responses of the individual to their own tissue constituents. "A recent report has suggested that an orphan G protein-coupled receptor 25 (GPR25), associated with blood pressure regulation and autoimmune disease, could be activated by both APLN and APELA in non-vertebrates, which is similar as APLN in decreasing the intracellular cAMP level." (PMID 33240613, 2020).
biliary atresia (1 paper, 2018). A rare, biliary tract disease characterized by progressive obliterative cholangiopathy of the intra- and extrahepatic bile ducts, occurring in the embryonic/ perinatal period, leading to severe and persistent neonatal jaundice and acholic stool. "Our results support the use of apelin as a prognostic factor in biliary atresia." (PMID 29535774, 2018).
bone fracture (1 paper, 2019). "At last, previous study has revealed that in normal healthy human subjects, the concentration of Apelin in plasma was 3.58 ± 0.33 ng/ml; unfortunately, it is unknown how plasma Apelin changed in bone fracture patients." (PMID 31238979, 2019).
carbohydrate metabolism disorders (1 paper, 2021). "Significantly lower apelin concentration in women with PCOS (>5 fold) than in women without PCOS, associated with a concomitant increase in leptin, may also contribute to carbohydrate metabolism disorders occurring in the course of PCOS." (PMID 34604014, 2021).
carotid atherosclerosis (1 paper, 2019). A thickening and loss of elasticity of the walls of carotid arteries that occur with formation of atherosclerotic plaques. "One study has demonstrated lower apelin levels in patients with carotid atherosclerosis." (PMID 31803136, 2019).
cholestasis (1 paper, 2025). Impairment of the bile flow caused by obstruction within the liver, or outside the liver in the bile duct system. "Studies have suggested that, in cholestatic liver injury, apelin signaling exacerbates liver damage and fibrosis, contributing to the progression of cholestasis." (PMID 39744169, 2025).
chondrosarcoma (1 paper, 2023). A malignant cartilaginous matrix-producing mesenchymal neoplasm arising from the bone and soft tissue. "In the present study, we found that APLN was highly expressed and secreted in Dox-resistant chondrosarcoma cells." (PMID 36614283, 2023). "The expression of APLN was also observed to be related to the malignancy of clinical chondrosarcoma tissue." (PMID 36614283, 2023). "Taken together, these findings will provide rationale for the development of drug resistance biomarkers and therapeutic strategies for APLN pathway inhibitors to improve the survival of patients with chondrosarcoma." (PMID 36614283, 2023). "To determine the correlation between APLN expression in chondrosarcoma clinical tissues and its progression, we analyzed APLN expression in low-grade and high-grade groups using tissue arrays." (PMID 36614283, 2023). "The results indicated that activation of the APLN pathway may contribute to Dox resistance in chondrosarcoma cells." (PMID 36614283, 2023). "However, it is largely unclear whether miRNAs can increase Dox sensitivity by regulating APLN in chondrosarcoma." (PMID 36614283, 2023). "Furthermore, knockdown of APLN can sensitize chondrosarcoma cells to Dox." (PMID 36614283, 2023). "Therefore, we wondered whether the expression of APLN is mediated by miRNAs to alter the Dox sensitivity in chondrosarcoma." (PMID 36614283, 2023). "Therefore, APLN pathway inhibitors may also be applied in the treatment of chondrosarcoma in the future to improve the survival rate of patients." (PMID 36614283, 2023). "Therefore, we performed in vitro experiments to verify the role of APLN in Dox resistance of chondrosarcoma cells, and the results showed that APLN was highly expressed and secreted in Dox-resistant cells, and APLN knockdown could restore Dox sensitivity in Dox-resistant cells." (PMID 36614283, 2023). "However, the role of APLN in chondrosarcoma is completely unclear, and no related studies have been reported." (PMID 36614283, 2023). "However, the functions and related mechanisms of APLN and APLN-related miRNAs have not been reported in chondrosarcoma." (PMID 36614283, 2023). "Thus, inhibition of the APLN–APLNR axis may become a new therapeutic target for a variety of cancers, including chondrosarcoma." (PMID 36614283, 2023). "However, the role of APLN and its related regulation in chondrosarcoma is completely unknown, and no related studies have been reported." (PMID 36614283, 2023).
Chronic colitis (1 paper, 2024). A chronic inflammatory disease of the large intestine (colon, cecum and rectum). "It was reported that adipokine apelin could ameliorate chronic colitis in Il10−/− mice by promoting intestinal lymphatic function." (PMID 39623906, 2024).
Chronic Hepatitis C (1 paper, 2011). "The present study was conducted to evaluate blood apelin level changes among 73 chronic hepatitis C (CHC) Egyptian patients and if associated with body mass index (BMI), IR, and tumor necrosis factor-alpha (TNF-α)." (PMID 22007137, 2011).